RXFP1 (relaxin family peptide receptor 1)
Diseases named in the same sentence as RXFP1 in open-access papers (continued):
Sharing a sentence is not in itself a finding about the gene and the disease.
endothelial dysfunction (2 papers, 2018 to 2025). In vascular diseases, endothelial dysfunction is a systemic pathological state of the endothelium (the inner lining of blood vessels) and can be broadly defined as an imbalance between vasodilating and vasoconstricting substances produced by (or acting on) the endothelium. "Targeting vasodilatory Gi-protein-coupled RXFP1 pathways may provide promising opportunities for drug discovery in endothelial dysfunction and cardiometabolic disease." (PMID 30233409, 2018). "Western blotting analysis revealed decreased expression levels of RXFP1, PI3K p55, and eNOS, as well as the reduced ratios of p‐AKT/AKT and p‐eNOS/eNOS in the DMED group, suggesting endothelial dysfunction in penis." (PMID 39654344, 2025).
lung carcinoma (2 papers, 2022 to 2024). "KIAA1429 promoted lung cancer by down-regulating RXFP1 expression in an m6A-dependent manner in lung cancer." (PMID 39456252, 2024). "In their study, RXFP1, RAMP2-AS1, LINC00312, and LINC00472 were identified as key lncRNAs in smoking-associated lung cancer; however, their area under the curve (AUC) value is 0.608 and is smaller than that in our study, indicating that our model is more accurate." (PMID 35529255, 2022).
lung diseases (2 papers, 2021 to 2022). "Evidence shows that RXFP1 appears to have a significant impact on lung diseases." (PMID 34039311, 2021). "There was some evidence that EDNRB, RXFP1, ANGPT1, and TEK are closely related to lung diseases and cancer." (PMID 34039311, 2021).
thyroid cancer (2 papers, 2015 to 2018). "RXFP1 mediated the motility-enhancing effect of RLN2 via induction of S100A4 in human thyroid carcinoma cells and RLN2 enhanced thyroid xenograft angiogenesis." (PMID 26322020, 2015). "Increased expression of RLN2 and RXFP1 was also shown in thyroid cancer." (PMID 26322020, 2015). "RLN2/RXFP1 signaling promotes thyroid cancer motility and invasiveness." (PMID 26322020, 2015).
acute myeloid leukemia (1 paper, 2025). Acute myeloid leukemia (AML) is a group of neoplasms arising from precursor cells committed to the myeloid cell-line differentiation. "RXFP1 expression is markedly elevated in leukemia cells, with 2.71-fold increases in acute myeloid leukemia (AML) and 3.31-fold increases in chronic myeloid leukemia (CML) compared with control populations (CD34+/CD38- stem cells and CD34+/CD38+ progenitor cells)." (PMID 41196672, 2025).
acute myocardial infarction (1 paper, 2020). Necrosis of the myocardium, as a result of interruption of the blood supply to the area. "In our results, after knockdown RXFP1 by specific RXFP1 siRNA, mast cell markers chymase and tryptase, inflammatory cytokines IL-6 and TNF-α, and classic phosphorylated NF-κB all increased, which was consistent with the acute myocardial infarction outcomes." (PMID 32859236, 2020).
bile duct cancer (1 paper, 2025). "Therefore, we confirmed the expression of LGR7/RXFP1 in cancer cell lines using immunoblotting, including the human pancreatic cancer cell lines (SU86.86, Panc-1, AsPC-1, AsPC-1-CD44v6, and MIA PaCa-2 cells), bile duct cancer cell lines (TFK-1, HuCCT-1, and NOZ), imhPSCs, and LNCap." (PMID 40666525, 2025).
depression (1 paper, 2023). "Before correction for multiple testing, rs74400983 (unadjusted p = 0.0232) and rs78161395 (unadjusted p = 0.0428) at RLN3, as well as rs62351166 (unadjusted p = 0.0388) at RXFP1 were nominally linked with the broad phenotype of depression; however, these did not withstand FDR corrections." (PMID 37967073, 2023).
endometrioid endometrial carcinoma (1 paper, 2018). "We then examined RLN2 and RXFP1 expression in 80 human endometrioid endometrial carcinoma tissues." (PMID 30126180, 2018). "Furthermore, the significance of RLN2 and RXFP1 was examined by immunohistochemistry in 80 cases of endometrioid endometrial carcinoma (EEC) tissues." (PMID 30126180, 2018).
glaucoma (1 paper, 2023). Increased pressure in the eyeball due to obstruction of the outflow of aqueous humor. "Given that relaxin signaling was down-regulated in GC-R HTM cells and relaxin mediates an anti-fibrotic activity through its cognate receptor (RXFP1), the role of relaxin in SI-OHT and glaucoma requires further studies." (PMID 38002955, 2023).
glioma (1 paper, 2022). A benign or malignant brain and spinal cord tumor that arises from glial cells (astrocytes, oligodendrocytes, ependymal cells). "Here, we have identified RXFP1 as a new member of a growing number of GPCRs that utilize the JAK‐STAT signaling pathways previously associated with cytokine and growth factor receptor signaling during development, inflammation, and tumorigenesis, including glioma." (PMID 33960104, 2022).
Hydrocephalus (1 paper, 2020). Hydrocephalus is an active distension of the ventricular system of the brain resulting from inadequate passage of CSF from its point of production within the cerebral ventricles to its point of absorption into the systemic circulation. "Our findings showed that rh-relaxin-2 attenuated degranulation of mast cells and neuroinflammation, improved neurological outcomes, and ameliorated hydrocephalus after GMH through RXFP1/PI3K-AKT/TNFAIP3/NF-κB signaling pathway." (PMID 32859236, 2020).
leukemia (1 paper, 2025). A malignant (clonal) hematologic disorder, involving hematopoietic stem cells and characterized by the presence of primitive or atypical myeloid or lymphoid cells in the bone marrow and the blood. "Relaxin signaling, primarily through RXFP1, has been implicated in disease contexts such as leukemia and preeclampsia, with elevated receptor expression linked to poorer survival in leukemia patients and decreased placental expression associated with later development of preeclampsia." (PMID 41196672, 2025). "Interestingly, the literature also suggests a correlation between high RXFP1 expression and poorer cancer-specific survival rates in leukemia patients, especially those with mutations in the RXFP1 gene." (PMID 41196672, 2025). "The influence of relaxin on leukemia is slowly becoming an important area of cancer research, particularly due to the significance of its receptor RXFP1." (PMID 41196672, 2025). "This association raises important questions about the clinical implications of RXFP1 in leukemia treatment and prognosis." (PMID 41196672, 2025). "While GR is expressed in all leukocyte populations, RXFP1 has so far been reported in lymphocytes, monocytes, and macrophages, as well as in certain progenitor and hematologic neoplasm (leukemia, lymphoma, and myeloma) cell lines." (PMID 41196672, 2025).
liver disease (1 paper, 2017). "Furthermore, there was a positive association between liver disease stage and the expression levels of RXFP1 transcripts." (PMID 28883402, 2017).
malignant glioma (1 paper, 2022). A grade III or grade IV glioma arising from the central nervous system. "RXFP1 activation by the secreted adiponectin paralog and RXFP1 agonist C1q tumor necrosis factor‐related peptide 8 (CTRP8) resulted in elevated intracellular cAMP levels and activated PKCζ and PKCδ isoforms in human malignant glioma." (PMID 33960104, 2022). "However, the ability of RXFP1 to engage the JAK3‐STAT3 signaling pathway provides a hitherto underappreciated new route of promoting GBM invasiveness and, in part, may explain the limited treatment success of JAK2 inhibitors in malignant glioma." (PMID 33960104, 2022).
memory impairment (1 paper, 2024). "Genes involved in neuroactive ligand–receptor interactions, such as Npy2r, Htr2c, and Rxfp1, were significantly dysregulated during cognitive dysfunction or memory impairment which was tightly related with tinnitus." (PMID 38562529, 2024).
Myocardial fibrosis (1 paper, 2025). "Studies on diseases such as myocardial fibrosis have shown that RLX‐2 can inhibit endothelial cell transformation into mesenchymal cells by activating the RXFP1/eNOS/NO pathway, thereby downregulating TGF‐β1/Smad/CTGF signaling and exerting antifibrotic effects." (PMID 39654344, 2025).
preeclampsia (1 paper, 2025). Preeclampsia is a hypertensive disorder of pregnancy that is characterized by new-onset hypertension with proteinuria presenting after 20 weeks of gestation, and depending on mild or severe forms may initially present with severe headache, visual disturbances, and hyperreflexia. "Additionally, lower placental RXFP1 expression has been observed in healthy individuals who later develop preeclampsia." (PMID 41196672, 2025). "RXFP1 could play significant roles in blood malignancies and preeclampsia." (PMID 41196672, 2025).
prostate tumor (1 paper, 2019). "Mutated H2-RLN, which functioned as an RXFP1 antagonist, impaired prostate tumor growth." (PMID 31278269, 2019).
small cell neuroendocrine carcinoma (1 paper, 2011). "Another potential target for the treatment of small cell neuroendocrine carcinoma is the relaxin receptor RXFP1." (PMID 22110988, 2011).
Ureteral obstruction (1 paper, 2021). Obstruction of the flow of urine through the ureter. "In the present study, we tested the hypothesis that ML290, a small molecule agonist of the human relaxin receptor (RXFP1), is able to target the kidney to remodel the extracellular matrix and reduce apoptosis induced by unilateral ureteral obstruction (UUO)." (PMID 34305630, 2021).
cancer (14 papers, 2011 to 2025). A tumor composed of atypical neoplastic, often pleomorphic cells that invade other tissues. "RXFP1 (Relaxin Family Peptide Receptor 1) overexpression inhibits the proliferation, migration, and invasion of cancer cells." (PMID 40723784, 2025). "These migratory effects were associated with chemotaxis toward MCP-1, a chemokine critical for recruiting leukocytes to sites of inflammation or cancer, and were shown to depend on the RXFP1/Gαs/adenylate cyclase/cAMP signaling axis." (PMID 41196672, 2025). "RXFP1, the relaxin-like family peptide receptor 1, has been established to mediate anti-apoptotic, angiogenic, and chemo-resistant functions in cancer cells." (PMID 39043730, 2024). "RXFP1 also was involved in anti-apoptotic functions, angiogenesis and chemoresistance in cancer cells." (PMID 36032660, 2022). "Studies related to relaxin/RXFP1 and human diseases have been centered on cancer and fibrotic diseases." (PMID 32100955, 2020). "RXFP1 activation was reported to mediate anti-apoptotic functions, angiogenesis and cell invasion in cancer." (PMID 32647070, 2020). "Both our in vitro analysis and previous report demonstrated that RXFP1 had a crucial role in RLN2-induced cancer invasion." (PMID 30126180, 2018). "RXFP1 immunoreactivity was detected in the cytoplasmic membrane of carcinoma cells, and RLN2 immunoreactivity was detected in the cytoplasm of carcinoma cells." (PMID 30126180, 2018). "The established role of RXFP1 in cancer and other diseases has prompted attempts to identify specific agonists and antagonists of RXFP1." (PMID 26322020, 2015). "In MCF-7 cancer cells and renal myofibroblasts endogenously expressing relaxin, the ΔH2 analog blocked RXFP1 activation and significantly inhibited RLN2-induced MCF-7 cell migration." (PMID 26322020, 2015). "The model signature genes RSPH9, RPS6KL1, RXFP1, and RTL1 have been revealed to be involved in cancer activity." (PMID 31886214, 2019). "Future cancer research activities will elucidate the molecular signaling mechanisms and functional relevance of CTRP-derived RXFP1 regulation in a variety of tumors." (PMID 26322020, 2015). "Its receptor, RXFP1 (a G-protein-coupled receptor), is expressed in androgen receptors' positive and negative cancers, as well as in prostate germ cells." (PMID 22110988, 2011).
tumor (11 papers, 2008 to 2025). "The activation of the G protein‐coupled receptor RXFP1 by RLN2 or CTRP8 has been associated with enhanced tumor cell motility and tissue invasion in several tumors, but the underlying molecular mechanisms remain poorly understood." (PMID 33960104, 2022). "Global transcription profiling revealed that RXFP1 siRNA significantly altered the expression of tumor-promoting genes." (PMID 41347146, 2025). "In both a murine HER2+ breast cancer model and an ex vivo brain metastasis system, RLN-2 increased TAM infiltration via RXFP1 activation, thereby fostering conditions that favor tumor growth and colonization." (PMID 41196672, 2025). "Intra tumor injection of RXFP1 siRNA resulted in downregulation of RXFP1 receptor expression and a significant reduction in tumor growth." (PMID 41347146, 2025). "The activation of the G protein‐coupled relaxin family peptide receptor 1 (RXFP1) promotes tumor growth, angiogenesis, migration, and tissue invasion in several human tumor types, including breast, thyroid, prostate, endometrium, and brain cancer." (PMID 33960104, 2022). "The close location of aHSC surrounding tumor cells within metastatic lesions facilitates the binding of paracrined RLN with RXFP1 on aHSCs." (PMID 31278269, 2019). "This suggests a novel and as yet poorly understood regulatory network in which C1q/tumor necrosis factor-related factors, depending on the presence of resident secreting cells, can modulate RXFP1 functions in a tissue-dependent and tumor-specific manner." (PMID 26322020, 2015). "Relaxin enhances proliferation, adhesion and invasion in vitro as well as tumour growth in the TRAMP mouse model in vivo, while deficiency of RXFP1 antagonizes this effect." (PMID 23963762, 2014). "Equally, RXFP1 was less frequently expressed in control tumours than in tumours from relaxin-treated mice (p < 0.01)." (PMID 23963762, 2014). "This is accompanied by increased serum concentrations of progesterone and estradiol as well as elevated expression of the respective receptors and the relaxin receptor RXFP1 in the tumour tissue." (PMID 23963762, 2014). "This was associated with a significantly higher proliferation rate in tumours from relaxin-treated animals as well as with upregulation of RXFP1 expression." (PMID 23963762, 2014). "Downregulation of its receptor, Rxfp1, dramatically reduced tumor growth, as evidenced by decreased proliferation and increased apoptosis of the xenograft tumor." (PMID 22984576, 2012). "Known for its role in pregnancy, RLN2 facilitates the softening and remodeling of collagen in the cervix and pelvic ligaments, and also promotes collagen degradation in the tumor microenvironment by upregulating matrix metalloproteinase levels by binding to the receptor LGR7/RXFP1." (PMID 40666525, 2025). "Notably, differentiated THP-1 cells exhibit the lowest RXFP1 expression, while macrophages within the tumor microenvironment show the highest RXFP1 levels." (PMID 41196672, 2025). "We then asked whether relaxin-3 exerts its effect via its specific receptor RXFP3 or via RXFP1 in both tumour cells and brain." (PMID 23963762, 2014). "Both receptors were present in the brain, but only RXFP1 was expressed on the tumour cells." (PMID 23963762, 2014). "Although we did not conduct an evaluation of distant metastasis during the long-term follow-up period using the subcutaneous tumor model, our investigation revealed that the RLN2 receptor LGR7/RXFP1 was expressed in multiple pancreatic and biliary cancer cell lines." (PMID 40666525, 2025). "In the tumour cells, we could detect only RXFP1 and 2, RXFP3 was absent (not shown for 4T1)." (PMID 23963762, 2014).
cardiovascular disease (4 papers, 2018 to 2023). "SA10SC-RLX represents a new class of long-lasting RXFP1 agonist, suitable for once daily subcutaneous administration in patients and potentially paving the way to new treatments for chronic fibrotic and cardiovascular diseases." (PMID 36443381, 2022). "This study is limited in that myocardial relaxin receptor (RXFP1) expression remains unknown in patients with cardiovascular disease, leaving the potential to improve myocardial perfusion uncertain." (PMID 32065620, 2021). "The activation of RXFP1 may play a protective role in cardiovascular disease." (PMID 36671033, 2023). "As a potent vasodilatory Gαi2-coupled receptor, targeting RXFP1 may represent a promising avenue to study Gi-coupled receptor based drugs in cardiovascular disease that may allow clarifying specific roles for Gαi2 and Gαi3 in response to GPCR activation directly in the vasculature." (PMID 30233409, 2018).
adenocarcinoma (1 paper, 2019). A common cancer characterized by the presence of malignant glandular cells. "The expression levels of RRAGB, RSPH9, RPS6KL1, RXFP1, and RTL1 mRNA were significantly lower and the RRM2 mRNA level was significantly higher in the high-risk group than those in the low-risk group in NSCLC adenocarcinoma of GSE11969." (PMID 31886214, 2019). "This signature and the genes RRAGB, RSPH9, RPS6KL1, RXFP1, RRM2, and RTL1 included in this model are independent biomarkers for prediction of overall survival of NSCLC adenocarcinoma." (PMID 31886214, 2019). "Our six-gene prognostic signature for NSCLC adenocarcinoma include RRAGB, RSPH9, RPS6KL1, RXFP1, RRM2, and RTL1 genes which are not contained in the previous gene signatures." (PMID 31886214, 2019).
immune disorders (1 paper, 2026). "RXFP1, not previously implicated in autoinflammatory or innate immune disorders, encodes the relaxin family peptide receptor 1, a G protein-coupled receptor involved in extracellular matrix regulation, anti-fibrotic pathways, and modulation of inflammatory cytokine production." (PMID 41596288, 2026).
infection (1 paper, 2022). The state of being infected such as from the introduction of a foreign agent such as serum, vaccine, antigenic substance or organism. "Intriguing results were reported from experiments showing the mRNA expression of the RXFP1 gene: WI-38 fibroblasts (but not HFL1) showed increased expression of this gene under conditions of HRV infection (361% for HRV-16 and 338% for HRV-2, p < 0.05) with relaxin." (PMID 35955554, 2022).
RXFP1 also shares sentences with these, for which no sentence is quoted: erectile dysfunction (3 papers); cardiomyopathy (2); African trypanosomiasis (1); autoimmune hepatitis (1); brain tumor (1); chronic heart failure (1); chronic kidney disease (1); Cirrhosis (1); dementia (1); diabetes mellitus (1); endometriosis (1); fibrosis (1); Hypertension (1); liver cirrhosis (1); malaria (1); metabolic syndrome (1); metastatic disease (1); non-alcoholic steatohepatitis (1); pancreatic cancer (1); pulmonary arterial hypertension (1); subarachnoid hemorrhage (1); Tinnitus (1).